S100A8 (S100 calcium binding protein A8)
Diseases named in the same sentence as S100A8 in open-access papers (continued):
Sharing a sentence is not in itself a finding about the gene and the disease.
breast carcinoma (continued). "Taken together, out data demonstrate that, at least in part, the phenotypic and molecular transitions seen in the mammary epithelial cells when co-cultured with breast cancer cells can be explained by the upregulation of S100A8." (PMID 33446797, 2021). "S100A8 is a secreted inflammatory mediator, is increasingly recognized as a biomarker in many solid tumors, including breast cancers." (PMID 34072157, 2021). "Our previous study demonstrated that HRD1 inhibited the growth and metastasis of breast cancer cells by targeting IGF-1R and that it sensitized breast cancer cells to tamoxifen by targeting S100A8 for ubiquitylation and degradation." (PMID 33588886, 2021). "S100A8/A9 binding to RAGE promoted lung metastasis playing an important role in breast cancer spread." (PMID 33567747, 2021). "Nonetheless, our finding that prognostic significance of S100A8+ ICs depends on HR status gives an important clue to the role of S100A8+ ICs in breast cancer progression since HR-positive tumors are generally less immunogenic compared to HR-positive tumors." (PMID 33146829, 2021). "The binding of S100A8/S100A9 to RAGE promotes breast cancer cell growth by inducing MAPK signalling." (PMID 32722137, 2020). "Transcriptome analysis of the PyMT tumors from p11-KO mice showed marked reduction in genes such as Areg, Muc1, and S100a8 involved in breast cancer development, progression, and inflammation." (PMID 33297495, 2020). "The pro-inflammatory proteins S100A8/S100A9 are abundant in MDSC exosomes from breast cancer model mice and is chemotactic for MDSCs in vitro." (PMID 30792719, 2019). "In mammary carcinoma cell-bearing mice, S100A8/A9 from myeloid and tumor cells bind to RAGE on MDSCs and promote MDSC migration and accumulation through the NF-κB signaling pathways." (PMID 30792719, 2019). "More recently it has been shown that the expression level of S100A8/9 in Her2-positive breast cancer patients was increased and the level of ER was decreased following the administration of S100A8/9 in the MCF-7 cell line." (PMID 31528166, 2019). "According to our data as well as other observations, the S100A8/A9 heterodimer can be considered as a potential biomarker for the proper diagnosis and prognosis of breast cancer." (PMID 31528166, 2019). "S100A8/A9 imaging shows that MDSCs are abundant in the pre-metastatic lung and correlate with the subsequent metastatic breast cancer burden." (PMID 30792719, 2019). "Kaplan-Meier analyses were used to compare the S100A8 low and high expression groups of breast cancer patients." (PMID 30456203, 2018). "Multivariate analysis confirmed that increased S100A8 expression was an independent factor for poor outcome in breast cancer patients." (PMID 30456203, 2018). "Most studies of S100A8 have revealed that the S100A8 mRNA level is increased in breast cancer tissue from patients with poor prognosis." (PMID 30456203, 2018). "AGER binding to S100A8/A9 promoted lung metastasis through actin polymerization and epithelial–mesenchymal transition in breast cancer." (PMID 29298878, 2018). "We aimed to investigate the correlations between S100A8 and clinical parameters in 140 breast cancer patients and assess the clinical prognostic value of S100A8 expression in the relapse of breast cancer patients." (PMID 30456203, 2018). "In our study, we measured the expression of S100A8 in breast cancer tissue by immunohistochemical staining." (PMID 30456203, 2018). "We also elucidated the different expression levels of S100A8 in breast cancer patients with different subtypes." (PMID 30456203, 2018). "In conclusion, this study identified S100A8 as a potential biomarker for relapse in breast cancer patients." (PMID 30456203, 2018). "The aim of this study was to examine the expression of S100A8 at the protein level in breast cancer cells." (PMID 30456203, 2018). "A few studies have uncovered that individual S100A8 plays a vital role in poor prognosis of breast cancer." (PMID 30456203, 2018).
breast carcinoma (continued). "S100A8-positive cells detected in breast cancer stroma are usually expressed by infiltrating immune and myeloid cells." (PMID 30456203, 2018). "The Cox regression analysis demonstrated that elevated S100A8 expression and tumor grade were independent prognostic factors for poor survival in breast cancer patients." (PMID 30456203, 2018). "This study aims to evaluate the clinical significance of S100A8 expression in breast cancer patients." (PMID 30456203, 2018). "S100A8/A9 stimulates breast cancer progression by activating key signaling pathways, such as IL-6-JAK2-STAT3, TNF-α-CXCL1/2, TGF-β, NF-κB, and MAPK." (PMID 30456203, 2018). "In our study, we confirmed that the mRNA level of S100A8 was increased in relapsed breast cancer patients, and an elevated expression level of S100A8 was significantly correlated with shorter OS and DFS in public microarray datasets." (PMID 30456203, 2018). "We identified for the first time S100A8 as the down-stream target of HRD1 in mediating its drug-resistant effects on breast cancer cells." (PMID 28423597, 2017). "And in the breast cancer cells, the increased secretion of S100A8/A9 exacerbated the resistance of breast cancer to doxorubicin with cyclophosphamide." (PMID 28423597, 2017). "Overexpression of HRD1 increased the response of breast cancer to Tamoxifen by inhibiting S100A8 expression." (PMID 28423597, 2017). "So far the protein level of S100A8 has been studied by immunohistochemistry and shown to be up-regulated in colorectal carcinoma, lung cancer, pancreatic cancer, breast cancer and thyroid carcinoma." (PMID 27462864, 2016). "Higher levels of MMP-9, S100A8 and S100A9 transcripts were each significantly associated with worse relapse-free survival over a 20-year interval when all breast cancers were considered." (PMID 25633981, 2015). "A potential function of S100A8/A9 as a driving factor for cell proliferation was reported in human breast cancer cells and neonatal keratinocytes." (PMID 25811984, 2015). "One study conducted on breast cancer cell line showed that extracellular treatments with S100A8 and S100A9 proteins induce cell proliferation, while intracellular recombinant expression of S100A8 and S100A9 block cancer cells grow." (PMID 25298751, 2014). "In a breast cancer mouse model, plasma samples from preclinical tumor-bearing mice compared with control mice show an upregulated protein expression of S100A8, S100A9, and LCN2." (PMID 22559235, 2012). "RNA knock-down of Ets-1 suppressed NO-induced expression of selected basal-like breast cancer markers such as P-cadherin, S100A8, IL-8 and αβ-crystallin." (PMID 22971289, 2012). "In the present study, we aimed to investigate whether S100A8/A9 participates in GC progression, similar to its role in melanoma and breast cancers, via MCAM." (PMID 40924339, 2025). "Thus, we believe that further experiments will help to elucidate the underlying mechanism(s) of S100A8 and S100A9 proteins in treatment-resistant ER+ breast cancer." (PMID 39057065, 2024). "In addition to modulating the tumor microenvironment and cell metabolism, S100A8/S100A9 enhances chemoresistance of breast cancer cells by activating pro-survival ERK1, ERK2 and ribosomal protein S6 kinas β1 pathways." (PMID 39830522, 2024). "However, a tissue microarray analysis of human breast cancer showed a connection between the expression of the S100A8 gene and unfavorable outcomes." (PMID 39594999, 2024). "In addition, we studied S100A8 protein expression using immunohistochemistry in 498 primary breast cancers from the same cohort." (PMID 37450087, 2023). "The S100A8 secreted by breast cancer cells was detected by ELISA as well." (PMID 38093319, 2023). "Furthermore, serum S100A8 levels were elevated in breast cancer patients compared to those with benign breast nodules." (PMID 38093319, 2023). "The level of S100A8/A9 was higher in breast cancer, relative to normal tissue." (PMID 38093319, 2023).
breast carcinoma (continued). "While the involvement of S100A8/A9 in breast cancer development has been documented, its prognostic significance and the precise regulatory mechanisms remain unclear." (PMID 38093319, 2023). "Elevated S100A8/A9 predicts poor prognosis of breast cancer patients." (PMID 38093319, 2023). "To verify this hypothesis, we first compared the values of the Cxc1-to-S100a8 ratio in the synthetic MNs and lungs of multiple animal models of breast cancer with varying tumor aggressiveness and host immunity." (PMID 37553342, 2023). "Similarly, the result of Kaplan-Meier survival analysis showed that high S100A9 and S100A8/A9 mean value were unfavorable factors for the OS of breast cancer patients." (PMID 38093319, 2023). "In addition, analysis based on TCGA breast cancer RNA-seq datasets showed the same trend that S100A8 and S100A9 mRNA was upregulated in ER-, PR-, and Her2 + patients (P < 0.0001)." (PMID 38093319, 2023). "The relationship between LOXL4 and S100A8/A9 in breast cancer progression remains to be discussed." (PMID 37091157, 2023). "Amplification of S100A8 does not appear to be associated with S100A8 protein expression in breast cancer." (PMID 37450087, 2023). "Coculture with breast cancer cells or induction of overexpression of S100A8/A9 revealed that normal epithelial cells exhibit features of EMT, and the capacity of cell proliferation, migration, colony formation, and three-dimensional sphere formation is increased." (PMID 36624542, 2023). "Similarly, the protein S100A8 is overexpressed in a roughly comparable proportion of breast cancers and is also found in infiltrating myeloid-lineage cells, again linked to poorer prognosis." (PMID 37450087, 2023). "Moreover, the binding of RAGE to S100A8/A9 promoted the migration and invasion of human breast cancer cells through actin polymerization and EMT." (PMID 35610613, 2022). "Moreover, extracellular S100A8/A9 can regulate breast cancer aggressiveness by inducing EMT via the MCAM/ETV4 axis." (PMID 35936690, 2022). "We then used syngeneic mouse mammary carcinoma model to determine whether the S100A8/A9 expression in mammary epithelial cells can be induced by adjacent murine mammary carcinoma cells in vivo." (PMID 33446797, 2021). "S100A8 expression levels are found elevated in several cancers, including breast cancer, which could be a biomarker in solid tumors." (PMID 34072157, 2021). "In those breast cancer patients, evaluation of S100A8+ IC may be helpful in planning additional treatment." (PMID 33146829, 2021). "Additionally, the upregulation of S100A8/9 in the breast cancer stromal tissues should be further examined by using a large dataset of triple negative breast cancer patients." (PMID 33446797, 2021). "Interestingly, primary tumor expressing ANGPTL7, MMP3, LCN2, S100A8, and ESM-1 levels that were upregulated in 4T1.2 cells was strongly associated with breast cancer patients’ survival outcomes." (PMID 34072157, 2021). "Despite the relatively high level of S100A8 expression in the lungs of naïve mice, the level of expression increased further and was significantly elevated after only seven days of tumor growth in a breast cancer model." (PMID 33567747, 2021). "S100A8/S100A9 activates the MAPK pathway to promote the proliferation of breast cancer (BC)." (PMID 34712325, 2021). "S100A8 is potential a prognostic biomarker in breast cancer and bladder cancer." (PMID 33240811, 2020). "This study revealed how S100A8/A9 binding to CD146 accelerates breast cancer growth and metastasis." (PMID 32782280, 2020). "Moreover, S100A8/S100A9 from mammary carcinoma cells bind to RAGE on MDSCs and promote the migration and accumulation of MDSCs through the NF-κB signaling pathways." (PMID 30792719, 2019). "Also, statistical analysis shows that the serum level of S100A8/A9 has 100% specificity and sensitivity (AUC = 1.00, 95% CI) for the diagnosis of breast cancer patients." (PMID 31528166, 2019).
breast carcinoma (continued). "Moreover, MDSC exosomes induce chemotaxis of MDSCs themselves through their S100A8 and A9 content and promote M2 macrophage polarization in breast cancer model mice." (PMID 30792719, 2019). "Currently, few studies have reported that S100A8 is also expressed by breast cancer cells." (PMID 30456203, 2018). "The expression level of S100A8 in breast cancer cells was detected by IHC." (PMID 30456203, 2018). "S100A8 is increasingly recognized as a biomarker in many solid tumors, such as head and neck squamous cell carcinoma, as well as colon, ovarian, bladder, and breast cancers." (PMID 30456203, 2018). "Therefore, the mechanism controlling different expression levels of S100A8 in subtypes of breast cancer remains to be discovered." (PMID 30456203, 2018). "Our study revealed that S100A8 was a promising predictor for relapse in breast cancer patients." (PMID 30456203, 2018). "The prognostic value of S100A8 was investigated in breast cancer by ROC curve analysis." (PMID 30456203, 2018). "To explore the significance of S100A8 in human breast cancer progression, we further examined whether S100A8 protein expression was different in paired normal human breast epithelium and breast carcinoma samples by immunoblotting methods." (PMID 30456203, 2018). "Recently, studies have shown that S100A8 is a potential indicator of poor survival in acute myeloid leukemia (AML), and increased mRNA levels of S100A8 were associated with progression in breast cancer." (PMID 30456203, 2018). "Increased S100A8 expression was detected in breast cancer patients with relapse." (PMID 30456203, 2018). "Demographic characteristics of breast cancer patients assessed for S100A8 expression (n = 140)." (PMID 30456203, 2018). "Furthermore, the results of immunofluorescence show that, HRD1 and S100A8 co-located in the cytoplasm of the breast cancer cells." (PMID 28423597, 2017). "Our results indicated that high mRNA expression of S100A8, S100A9, S100A11 and S100P were found to be significantly correlated to worse outcome, while S100A1 and S100A6 were associated with better prognosis in all breast cancer patients." (PMID 28051137, 2017). "S100A8 plays an important role in chemotherapy resistance and metastasis of breast cancer." (PMID 28423597, 2017). "Among these identified proteins, S100A8 is related to chemoresistance of breast cancers." (PMID 28423597, 2017). "In this study, we examined the expression of HRD1 in MCF7/Tam and MCF7 cells and investigated its function in degradation of S100A8, in order to better understand its role in chemistry-drug resistance of breast cancer and its potential implications for cancer therapy." (PMID 28423597, 2017). "Using a murine model of metastatic breast cancer, we present the first in vivo visualization of systemic tumor-mediated effects on immune cells and establish S100A8/A9 as a surrogate marker for immunomodulation in the context of pre-metastatic lung tissue priming." (PMID 28744322, 2017). "In breast cancer, lungs and livers could highly express S100A8 and facilitates the recruitment of MDSCs in these metastatic foci, which promote the metastasis of breast cancer." (PMID 27542274, 2016). "Interestingly, S100A8 has been found to be upregulated incolorectal carcinoma, lung cancer, pancreatic cancer, breast cancer and thyroid carcinoma." (PMID 27462864, 2016). "Furthermore, RAGE-binding S100A8/A9 promoted the migration and invasion of human breast cancer cells through actin polymerization." (PMID 26412984, 2015). "Interestingly, the S100A8/A9¬–MCAM–ETV4–ZEB1 axis is promoting the aggressiveness of breast cancer." (PMID 41009692, 2025). "Moreover, elevated S100A8/A9 predicted a worse prognosis for breast cancer patients." (PMID 38093319, 2023). "Therefore, we used S100A8 as the surrogate to explore the expression of S100A8/A9 in breast cancer." (PMID 38093319, 2023).
breast carcinoma (continued). "Here, we hypothesized that the N1-to-N2 chemoattractant ratio, such as the Cxcl1-to-S100a8 gene ratio, could be a better biomarker to predict the survival of breast cancer patients than the single gene since the ratio can indicate whether N1 is the dominant neutrophil phenotype in the MNs." (PMID 37553342, 2023). "Additionally, S100A8/A9 is positively correlated to breast cancer metastasis and chemoresistance." (PMID 38093319, 2023). "Initially, we thought that S100A8 mainly plays a role in premetastatic niche formation, but several studies have reported that various types of cancer cells also express TLR4 at the cell surface, and that its expression is associated with poor prognosis in breast cancer and other types of cancer." (PMID 36932197, 2023). "Our results show that S100A8/A9, potentially critical regulators of cell behavior, could be induced in non-tumorigenic mammary epithelial cells during the dynamic cell–cell interactions with adjacent breast cancer cells." (PMID 33446797, 2021). "In conclusion, our results suggest that dissimilarly expression of few mediator encoding genes ANPTl7, MMP3, S100A8, LCN2 ESM1 in primary versus distant metastasis organs and their prognostic and predictive scores in breast cancer cohort may be a helpful to predict future metastasis." (PMID 34072157, 2021). "It has reported that strong expression and secretion of S100A8/S100A9 may be associated with the loss of estrogen receptor in breast cancer, and may be involved in the poor prognosis of Her2+/basal-like subtypes of breast cancer." (PMID 31208368, 2019). "High level of S100A9 but not that of S100A8 was found to be associated with loss of ER and the poor overall survival of breast cancer patients and to be involved in the poor prognosis of Her2+/basal-like subtypes of breast cancer." (PMID 29416786, 2018). "Moreover, S100A8 expression was correlated with clinical subtype in breast cancer patients." (PMID 30456203, 2018). "Therefore, HRD1 mediated breast cancer resistance by directly inhibiting S100A8 expression." (PMID 28423597, 2017). "Transcriptomic analysis revealed upregulation of macrophage activation markers, genes such as S100A8, S100A2, KRT81, KRT6C, MARCO and MMP1, as well as processes related to keratinization and the formation of a cornified envelope in breast cancer cells." (PMID 41073799, 2025). "They found that adding S100A8 and S100A9 proteins to the MCF7 breast cancer cell line extracellularly promoted cell growth." (PMID 39594999, 2024). "The S100A8 and S100A9 members are among the S100 inflammatory proteins shown to modulate several breast cancer processes as progression and malignancy." (PMID 39594999, 2024). "We examined S100A8, IL-6, IL-6R, IL-8, and CXCL3 genes; each of these are known to be differentially expressed in breast cancer and are being evaluated as biomarkers and therapeutic targets." (PMID 39199680, 2024). "Results showed that ionizing radiation and estrogen affected the expression of those genes that encoded the S100 calcium-binding proteins such as S100P, S100A14, S100A2, S100A8, and S100A9 in the immortalized breast cancer cell line MCF-10F." (PMID 39594999, 2024). "Such authors elucidated the roles of intracellularly produced S100A8 and S100A9 on critical signaling pathways and biological mechanisms responsible for the malignancy of breast cancer." (PMID 39594999, 2024). "It is noteworthy that the combined assessment of S100A8/A9 and DACH1 provides a more precise means of predicting outcomes for breast cancer patients, potentially serving as a promising biomarker for risk classification and prognosis prediction." (PMID 38093319, 2023). "The combination of S100A8/A9 and DACH1 predicted the overall survival of breast cancer patients more preciously." (PMID 38093319, 2023).